ZAP70 (zeta chain of T cell receptor associated protein kinase 70)
Diseases named in the same sentence as ZAP70 in open-access papers (continued):
Sharing a sentence is not in itself a finding about the gene and the disease.
tumor (continued). "Engagement of the antigen-specific TCR and CD28 costimulatory molecule by tumor cells or antigen-presenting cells triggers a T cell signaling cascade involving ZAP70, PI3K, and RAS pathways." (PMID 34054817, 2021). "ZAP70, a 70 kDa tyrosine kinase of the Syk family, has been reported to significantly promote tumor angiogenesis and immunosuppression in cancer cell lines or samples." (PMID 34133324, 2021). "In tumor coculture assays, the anti-HLA-G scFv moiety promotes Syk/Zap70 activation of NK cells, suggesting reversal of the HLA-G-mediated immunosuppression and hence restoration of native NK cytolytic functions." (PMID 34663641, 2021). "Antagonizing ZAP-70 inhibition by siRNA against Rasal1 increased the number of CD8+ tumor-infiltrating T-cells expressing granzyme B and interferon gamma (no ‘1') and enhanced tumor killing." (PMID 33194762, 2020). "Recent evidence also suggests that ZAP-70, intrinsically expressed in tumor cells, can modulate the cross-talk between malignant B cells and the immune environment, implying a more complex role of ZAP-70 in the pathogenesis of B cell malignancies." (PMID 33194762, 2020). "In a recent study the GTPase-activating protein (GAP) Rasal1, which inhibits ZAP-70, has been identified to suppress anti-tumor immune-responses." (PMID 33194762, 2020). "Mounting evidence indicates that the ZAP-70 expressed in tumor cells has ramifications for the composition of immune cells in the microenvironment, especially for the number of infiltrating T cells." (PMID 33194762, 2020). "Efforts have been made to understand the molecular role of tumor-intrinsic ZAP-70 expression in B cell malignancies." (PMID 33194762, 2020). "Recently studies have implied that tumor intrinsic ZAP-70 expression modulates the cross-talk between malignant B cells and their environment, suggesting a new angle to understand the role of ZAP-70 in these diseases." (PMID 33194762, 2020). "Here we review the evidences of the link between ZAP-70 and tumor immunology in the microenvironment in B cell malignancies." (PMID 33194762, 2020). "Tumor intrinsic expression of ZAP-70 in B cell malignancies has been shown to enhance cellular signals under ligand stimulated BCR activation." (PMID 33194762, 2020). "Paired tissue analysis in 3 patients identified ARG, AXL, TYRO3 and ZAP70 as increased in tumor relative to adjacent normal." (PMID 28423512, 2017). "The expression of several lymphocyte signaling molecules, including CTLA4, LAT, PDCD1, and ZAP70, was maintained in the transition from human tumor to CX, and was particularly prominent in the CXs derived from D61540." (PMID 24278200, 2013). "The dysfunctional lytic phenotype was subsequently shown to be due to a tumor-induced block in proximal TCR-mediated signaling that obviates ZAP70 activation, in turn due to rapid inactivation of p56lck upon contact with cognate tumor cells." (PMID 22567129, 2012). "Similarly, binding of TIGIT on T cells to CD155 on tumor cells and APCs can downregulate activation of ZAP70 and NF-κB in T cell intracellular signaling, which in turn inhibits T cell activation." (PMID 40276607, 2025). "Moreover, the lymphocyte cell‐specific protein tyrosine kinase LCK phosphorylates the ZAP70 protein (ζ chain of TCR‐associated protein kinase 70), and we measured a fourfold increased LCK activity in tumour biopsies of LC patients." (PMID 39995112, 2025). "Several tumor types have significant levels of ZAP70 expression." (PMID 40005847, 2025). "ZAP-70 induction in CLL B cells causes activation of specific BCR-signaling molecules, including SYK, BLNK, ERK, JNK, PLCγ, and AKT kinases, indicating ZAP-70 promotes the growth and survival of the tumor cells by stimulating BCR signaling." (PMID 38571491, 2024).
tumor (continued). "In lymphocytic leukemia, various aberrant signaling pathways in tumor microenvironment, including ZAP-70 protein, MAPK, and STAT3, stimulate the expression of post-translational regulator microRNA (miR-21) and other tumor suppressor genes (PTEN, PDCD4, and PIAS3)." (PMID 38590645, 2024). "Lower expression of AQP9 and ZAP70 was found in tumor tissues compared to normal tissues." (PMID 35477402, 2022). "In addition to engaging in tumor cell intrinsic signaling, likely improving the cellular fitness of tumor cells, evidence suggest that ZAP-70 expression is also involved in the cross-talk between malignant B cells and their microenvironment." (PMID 33194762, 2020). "In addition, correlations between the resistance of tumor cells to vincristine and the expression of Ki-67 (r = 0.13) and ZAP-70 (r = 0.61) were detected." (PMID 31067780, 2019). "This downregulation may contribute to the aggressive phenotype observed in ZAP-70+ cases; miR-29a, another tumor suppressor, is also reduced in ZAP-70+ CLL, allowing overexpression of oncogenic targets like TCL1 and anti-apoptotic proteins such as MCL1, thereby promoting survival and proliferation." (PMID 40981381, 2025). "Of note, ZAP70 activation seems to be a common feature of tumor cells, even for T-leukemic cells, transformed from very early progenitor T cells, which may lack TCR expression, thus guaranteeing YAP in an active form as well as the downregulation of FLNA in T-leukemic cells." (PMID 38360940, 2024). "Additionally, we performed correlation analysis to corroborate the relationship between tumor infiltrated immune cells and the expression of the seven key hub genes (CTLA4, PRF1, LCK, CD3E, CD247, ZAP70, and LCP2) in ARID1A-PIK3CA mutational co-occurrence tumors." (PMID 38017109, 2023). "Furthermore, we compared the expression of AQP9 and ZAP70 in tumor and normal tissues." (PMID 35477402, 2022). "Therefore, targeting ZAP-70 may exert anti-tumor effects not only through the modulation of signaling cascades in malignant B cells, but also through inhibition of cells resident or recruited to the tumor microenvironment." (PMID 33194762, 2020). "Inhibitory immune checkpoints such as PD-1 binding to PD-L1 (on tumor cells and APCs) can recruit SHP2 and downregulate the phosphorylation of ZAP70 and PI3K in T cell intracellular signaling, thus driving T cells toward inactivation." (PMID 40276607, 2025). "Mechanistically, CD8α:MyD88 signaling increased ZAP-70, ERK1/2, JNK, and p38 activation, reducing the response threshold in tumor-specific CD8+ T cells." (PMID 40948803, 2025). "By detecting the phosphorylation level of well‐established TCR downstream kinases including ZAP70, LAT, and ERK, we found that T cells were activated after culturing with medium from tumor cells treated with either DU101 or DU102 or with Arf1 knockdown." (PMID 39225354, 2024). "VAV family proteins, CD3g, ZAP70 and LCK were down-regulated at four weeks in comparison to one week, suggesting a downregulation of T-cell response in PAK4KO tumour over time." (PMID 38797819, 2024). "To evaluate the relationship between the expression of UGT2B17 and ZAP70, we initially studied the GSE21029 data set that provides gene expression from purified tumor cells obtained concurrently from blood, bone marrow, and lymph nodes of CLL patients." (PMID 37174695, 2023). "When PD-1 on the T cell surface interacts with PD-L1 on tumor cells, the phosphorylation of TCR signaling mediators such as Zap-70, Ras, and Akt decreases." (PMID 37205112, 2023). "As indicative of an enriched immune tumor microenvironment, we found CXCR3, ZAP70 and PTPN22; whereas others, such as TIMP1 and MAP2K3, had higher correlation with endothelial markers indicative of a tumor-induced angiogenic process." (PMID 35875157, 2022).
tumor (continued). "In this study, using RNA-seq data of 576 HCC patients, a panel of seven genes (including LCP2, TYROBP, ZAP70, PTPRC, FYN, WAS and NCF4) has been identified which are independent predictors of delayed tumor recurrence and improved patient prognosis." (PMID 34834481, 2021). "To date, it remains an important but unanswered question whether ZAP-70 expression levels in T and NK cells are associated with patient responses to immunotherapies, but an increasing amount of evidence suggests that ZAP-70 deficiency or inhibition can contribute to impaired tumor-surveillance." (PMID 33194762, 2020). "Immunohistochemical staining analysis demonstrated that more than half of the patients exhibited phosphorylated ZAP70, ITK and PLCγ1 in tumor tissues of AITL patients, suggesting the continuous activation of the TCR signaling in AITL." (PMID 30814910, 2019). "In contrast, the expressions of RAC2 (p = 0.0405), ZAP70 (p = 0.0121), IL2RG (p = 0.0175) and CD247 (p = 0.0112) were downregulated in tumour tissues." (PMID 29967488, 2018). "Ectopic expression of ZAP-70 induced transcription of miR-21 via MAPK and STAT3, which subsequently induced downregulation of tumor suppressors targeted by miR-21." (PMID 28947822, 2017). "The top 10 unpaired normal (n=4 samples) to tumor (n=11 samples) increased protein kinases were SYK, ZAP70, ARG (ABL2), ERBB3, ABL, TEC, MER (MERTK), AXL, EGFR and ERBB2." (PMID 28423512, 2017). "To further assess the effect of tumor-MDSC on early stages of T cell activation, we measured the expression of phospho-Zap-70 (pY319), a major kinase related with early stages of T cell receptor (TCR) signaling." (PMID 27007050, 2016). "We then searched for potential correlations between ZAP70 expression and known genetic abnormalities within the B-ALL tumours." (PMID 22548957, 2012). "Further investigation revealed that the TCR signaling pathway was significantly activated in hCT3 AbTCR T cells after co-culturing with NBEB tumor cells for 2 h compared to mock, CT3 CAR, and CT3 AbTCR T cells, with increased expression of phosphorylated ZAP70, SLP76, and LAT." (PMID 41027430, 2025). "Meanwhile, targeting the PTMs of key signaling molecules involved in TCR activation, such as ZAP70 and LAT, could restore T cell activity, enhance tumor recognition, and improve the anti-tumor immune response." (PMID 40040703, 2025). "Thus, we developed CD33 CAR constructs overexpressing LCK, ZAP70, C-JUN, C-Fos, and IFN-γ, and that overexpressing IL-15, a cytokine known to potentiate CAR T therapeutic activity in various tumor models, as a control." (PMID 39039086, 2024). "Even though CD28-based CAR-T cells had similar ZAP70 activation dynamics as 4-1BB-based CAR-T cells, they displayed slightly enhanced ERK activation, which may contribute to their faster anti-tumor kinetics in vivo." (PMID 35252208, 2022). "Since PD-1, ZAP-70, CD28 and CCR7 are all normally expressed in immune cells, the co-expression of these markers may reflect a tumor environment that promotes anti-tumor immunity." (PMID 35203305, 2022). "The anti-HLA-G scFv may compete with LILRB1 and KIR2D4 receptors on NK cells for HLA-G protein on the tumor membrane, thereby activating NK cell cytotoxicity by downregulating phosphorylated SHP-1 and upregulating phosphorylated Syk/Zap70." (PMID 34663641, 2021). "It has been suggested that the inhibition of ZAP-70 tyrosine-phosphorylation is a mechanism of CTLA-4 mediated suppression of CD4+ T activation, indicating a central role of ZAP-70 kinase activity in T cell activation and anti-tumor immune responses." (PMID 33194762, 2020). "Meanwhile, the indispensible roles of ZAP-70 in T cell and NK cell activation also demonstrate that the autologous expression of ZAP-70 in the immune environment can be a central target in modulation of tumor immunity." (PMID 33194762, 2020).
tumor (continued). "For the non-irradiated tumor in β2-AR KO mice, we noted a significant increase in expression of several genes including Cd28, Il2, and Zap70; genes showing the greatest decrease included genes which can inhibit effector function (including Il6 and Il10)." (PMID 32286326, 2020). "In studies comparing the immune-phenotype of ZAP-70 positive and ZAP-70 negative CLL patients, tumor ZAP-70 expression was associated with increased CD4 central memory T cells and CD3/CD69+ T cells with decreased CD4/CD8 ratio in the peripheral blood." (PMID 33194762, 2020). "Upon activation of TCR and CD28, transient phosphorylation of ZAP70 and PI3K/AKT would first occur and lead to downstream cascaded activation of ERK and NF-κB, which can promote the production and secretion of IL-2 and IFN-γ by T cells to enhance anti-tumor cytotoxicity." (PMID 40276607, 2025). "However, within the tumor microenvironment, CD274 expressed on tumor cells engages CD279 on immune cells, leading to phosphorylation of immunoreceptor tyrosine motifs, recruitment of SHP1/2, and inhibition of ZAP70 and PI3K signaling." (PMID 41409271, 2025). "CAR T cells overexpressing LCK effectively controlled tumor progression at an early stage, but the effect was not as long-lasting as that of ZAP70 or C-JUN, whereas overexpression of C-JUN showed the greatest effect in improving tumor control and prolonging mouse survival." (PMID 39039086, 2024). "The anti-HLA-G scFv component may compete with LILRB1 and KIR2D4, both of which are expressed by NK cells, to hijack tumor HLA-G and activate NK cell cytotoxicity by downregulating phosphor-SHP-1 and upregulating phosphor-Syk/Zap70 (thereby converting inhibitory signals to activating signals)." (PMID 34663641, 2021). "Moreover, these genes may play important roles in promoting tumor angiogenesis (CXCL13, ZAP-70, and CCL19), tissue remodeling (ITGAM and ITGB2), and immunosuppression (CD4 and IL-10) in cancer cell lines or samples." (PMID 32509861, 2020). "Thus, downregulation of ZAP70 and CD247 expression in this pathway may lead to an attenuation of NK cell-mediated cytotoxicity of the tumour, which in turn leads to the occurrence of PTC." (PMID 29967488, 2018). "Since ZAP-70 is normally not expressed in mature B cells, its expression in CLL and other mature B cell-derived neoplasms likely points to their different cellular origin." (PMID 33194762, 2020). "A divergent pattern of phosphorylation of Zap70, LAT, Akt and STAT6 was noted in patients with or without an objective tumor response." (PMID 20856802, 2010).
cancer (34 papers, 2010 to 2025). A tumor composed of atypical neoplastic, often pleomorphic cells that invade other tissues. "Among them, 8 of 12 hub genes (EPHX3, SPINK7, FCRLA, MASP1, ZNF541, CD5, BEST2, ZAP70) seemed to be cancer-promoting genes as they were downregulated in the high-risk group." (PMID 35846149, 2022). "In other words, the ZAP70 missense variant (rs104893674 (C > A)) increases susceptibility of distinct cell populations of different (myeloid and lymphoid) lineages to exhibiting cancer phenotype." (PMID 39113054, 2024). "Collectively, this early evidence demonstrates artificially controlling ZAP70, or variants of ZAP70 with different signaling thresholds, could be powerful tools for cancer immunotherapy." (PMID 34012443, 2021). "CD8+ cytotoxic T cells had elevated expression of the cytotoxic markers PD-1, Gzmb, Gzmk, Prf1, Nkg7, Eomes, Irf8, Klrd1, Fyn, Nfatc1, Tnfrsf9, and Zap70, supporting their killing function against cancer cells." (PMID 37762216, 2023). "Due to its upstream role in TCR signaling, ZAP70 has been gaining interest in the world of cancer-immunotherapy." (PMID 34012443, 2021). "Among drug-interactions obtained, Staurosporine has been reported to target ZAP70, but their interaction in cancer research is still blank." (PMID 32733542, 2020). "The hub genes in modules with high correlation, such as ZAP70, RPS27A, GRP1, SLC39A1, APOBEC3G, and GZMA, could provide insights into the molecular mechanisms underlying cancer progression." (PMID 40395456, 2025). "However, data on protein expression levels from the HPA database indicate that ZAP70 expression is higher in cancer tissues than in normal kidney tissues." (PMID 40104395, 2025). "Interestingly, five genes (CD247, CD3E, ZAP70, LCK, PTPN6) were associated with the hsa05235 pathway (PD-L1 expression and PD-1 checkpoint pathway in cancer)." (PMID 34880861, 2021). "The cause of Th1 and Th2 count alteration in cancer immunity is not clear; however, the shifting of the Th1 cytokine profile to Th2 seems to be associated with ZAP70." (PMID 26376785, 2016). "Knowledge about ZAP-70 expression in malignant neoplasms is still scarce." (PMID 22743590, 2012). "To further verify the importance of CD61 in regulating Zap70 phosphorylation, we then evaluated the Zap70 (pY292) expression on WT CD61+ T cell lines from seven different patients with cancer." (PMID 38561495, 2024). "The analysis of the KEGG pathway showed that this pathway was enriched in IL12-mediated signal transduction, ZAP70 to immune synaptic enzyme, second messenger molecule production, and TCR signal transduction and was also involved in many cancers." (PMID 35996545, 2022). "In agreement, we demonstrated that treatment with αCD61 neutralizing antibody led to a significant downregulation of Lck expression on WT CD61+ T cell lines of seven different patients with cancer, suggesting that CD61 is a modulator of Lck-dependent Zap70 phosphorylation." (PMID 38561495, 2024). "Similarly, genes involved in T cell mediated immune response, such as CD3D, CD3E, CD3G, CD247 in the CD3-TCR complex and downstream effector ZAP70, were more rapidly repressed in LUSC than in LUAD, especially at the early cancer stage." (PMID 27863400, 2017). "In contrast, immune-related kinases (ZAP70, SYK, ITK, and CSF1R) displayed reduced activity, implicating dampened immune signaling in pathways like PD-L1 Expression and PD-1 Checkpoint in Cancer (hsa05235), T Cell Receptor Signaling (hsa04660), and B Cell Receptor Signaling (WP23)." (PMID 41387887, 2025). "The protein encoded by this gene was phosphorylated by ZAP-70/Syk protein tyrosine kinases following activation of the T-cell antigen receptor (TCR) signal transduction pathway 32, Interestingly, the role of LAT gene in cancers has never been reported." (PMID 31777602, 2019).